IL17A (interleukin 17A)
Diseases named in the same sentence as IL17A in open-access papers (continued):
Sharing a sentence is not in itself a finding about the gene and the disease.
colitis (continued). "Those that were upregulated by 1 log fold or higher include IL-9, IL-13, IL-4, IL-17A, IL-5, IL-24, IFN-γ, IL-10, IL-11, and IL-27, many of which are known cytokines involved in the pathogenesis of colitis." (PMID 21365015, 2011). "We examined levels of IL-6, IL-10, IL-17A, and IL-23 in the colons following 7 days of cis-UCA treatment, and also following the induction of colitis." (PMID 21060867, 2010). "We found that oral administration of IPA attenuated mucosal inflammation in both acute and chronic colitis models in mice, as characterized by increased body weight, and reduced levels of pro-inflammatory cytokines (e.g. TNF-α, IFN-γ, and IL-17A) and histological scores in the colon." (PMID 39956891, 2025). "To further determine which TH17 cytokines are responsible for inhibiting chemokine expression and protect the Tak1ΔM/ΔM mice against colitis and CRC, we performed intracellular staining of key TH17 cytokines (IL-17A, IL-17F, IL-21, and IL-22) in CD4+ cells from intestinal LP." (PMID 40749055, 2025). "Additionally, in the DSS‐induced acute colitis model, OLE suppresses Th17 responses by decreasing the CD4+ Rorγt+ IL‐17+ IFN‐γ + T‐cell subset in the submucosal layer of the intestines, along with lower expression levels of IL‐17A and IFN‐γ." (PMID 40548181, 2025). "After DSS treatment, IL-17RC KO in Tak1ΔM/ΔM mice completely converted the resistant phenotype to the sensitive phenotype, suggesting that IL-17RC receptor is required for IL-17A–mediated inhibition of chemokine expression and resistance to DSS-induced colitis." (PMID 40749055, 2025). "The mechanisms through which CSCC protects against DSS-induced colitis may include upregulating Gpr43, inhibiting the STAT3/NLRP3 pathway, and suppressing inflammation factors like IL-17A." (PMID 39329121, 2024). "The role of IL-17A/F has been extensively investigated across various colitis models, yet the findings have not provided a definitive consensus." (PMID 39379604, 2024). "In the case of naïve cell–induced colitis, IL-17A of T cell as well as type 3 ILC origins redundantly contribute to pathogenesis of inflammation, suggesting that ILC3s also play a role in the MP cell responses through IL-17A production in the gut." (PMID 39630890, 2024). "During the colitis phase, cells were harvested, cultured with phorbol 12-myristate 13-acetate and ionomycin, and subsequently stained for CD3/CD4, followed by fixation, intracellular staining for IL-17A and IFNγ, and analysis using flow cytometry (FCM)." (PMID 39596393, 2024). "SNS significantly reduced colonic inflammation, similar to the effects of vagus nerve stimulation (VNS), by modulating autonomic function and cytokine production (decreased TNF-α, IL-6, and IL-17A, increased IL-10), indicating potential therapeutic utility for IBD treatment." (PMID 39605787, 2024). "The key cytokines involved in colitis, such as TNF-α, IL-17A, and IL-1α, were used to test whether DSS-induced downstream cytokines restricted NEDD4L expression." (PMID 39688910, 2024). "Although macrophages, due to their exceptional plasticity during colitis and cancer progression, could be pleiotropic orchestrators for pro- or antitumor immunity, IL23 and IL17A are known promoters of early CRC." (PMID 38258906, 2024). "In conclusion, the role of the IL-17A-inhibitors in the development of colitis remains not fully understood and requires further investigation." (PMID 38060157, 2024). "Interestingly, while blocking IL-17A can exacerbate colitis, perturbation of IL-17F has been reported to reduce disease activity in a DSS-induced colitis model." (PMID 39379604, 2024). "In a model of Hh-induced colitis following the transfer of naïve T cells, IL-23 plays a pivotal role in the induction of IL-17A+ IFN-γ+ Th cells rather than IL-17A+ IFN-γ- T cells." (PMID 39379604, 2024).
colitis (continued). "Interestingly, when we treated the infected colitis mice with LGG or BL, we observed a significant increase in IL-6, CXCL2, IL-1β, TNF-α, IL-17a, and IL-22 gene expression in the cecal tissue, indicating an enhanced inflammatory response." (PMID 38397855, 2024). "IL-17a had the highest level in the group of obese TNBS colitis mice without IAP administration and treatment with IAP significantly decreased (p < 0.05) the plasma levels of this cytokine." (PMID 38255781, 2024). "Our results demonstrated that the cecal gene expression of IL-6, CXCL2 (murine IL-8 homologue), IL-1β, TNF-α, IL-17a, IL-22, and CRAMP (homologue of human cathelicidin LL-37) was significantly elevated in the mice with P. aeruginosa-infected colitis after chemotherapy." (PMID 38397855, 2024). "Though we suspect that altered Th17 cell trafficking and function play a role in reduced disease in WIN 18,446-treated Mdr1a−/− mice, we did not observe changes in serum IL17F or IL17A associated with WIN 18,446 treatment or colitis severity." (PMID 37764666, 2023). "Interestingly, pre-treatment of only N5 decreased the number of Th17 cells and their IL-17a production in PP compared to the health control group and pre-treatment of N5 reduced these parameters in DSS-induced colitis." (PMID 38033603, 2023). "We suggest that although mucosal B cells are initially required to ameliorate ETBF-mediated colitis, they do not affect the IL-17A response to ETBF colitis." (PMID 38203534, 2023). "We then analyzed the effect of L. intestinalis on DSS‐induced colitis in Rag1−/− mice lacking T cells and mice treated with IL‐17A neutralizing antibodies (αIL‐17A)." (PMID 37983567, 2023). "Moreover, we show for the first time that a novel microbiota-derived metabolite, 12-KLCA, exhibits a powerful anti-inflammatory effect in DSS-induced colitis by increasing the VDR expression and decreasing the IL-17A secretion in colonic ILC3s." (PMID 38062857, 2023). "Previous reports found that during DSS induced colitis, mice with a mutation to constitutively activate TRPV1 showed a significant increase in CD4+ T cells producing IL-17A but not IFNγ." (PMID 38109366, 2023). "Additionally, Fuc-S also successfully prevented colitis by inhibiting the production of TNF-α, IFN-γ, IL-6, and IL-17A in the colons of colitic mice." (PMID 36662189, 2022). "In contrast, the numbers as well as percentages of IFNγ or IL-17A–expressing CD8+ T cells were not changed in mice with colitis." (PMID 35844584, 2022). "Here, IL-17A and IFNγ production was strongly increased in CD4+ T cells from mice with colitis." (PMID 35844584, 2022). "Trim27 deficiency could decrease the levels of pro-inflammatory cytokines (IL-6, TNF-α, and IL-17A) in the colonic mucosa and suppress the DSS-induced colitis." (PMID 35565775, 2022). "The administration of antibiotics inhibited the IL-17A, IL-17F and IFNγ-expressing cells in the LILP of both WT and Rap1KO mice, and prevented the development of colitis, indicating that colitis is developed in microbiota-dependent manner in Rap1KO mice." (PMID 35246619, 2022). "As for colitis, it has been shown that TRM cells are increased in the gut of patients with IBD and have a pro-inflammatory phenotype that CD69+ T cells expressed higher levels of IFNγ, IL-13, IL-17A, and TNF mRNA than CD69− T cells." (PMID 35844584, 2022). "The numbers of CD69−CD103− T cells and CD69+CD103+ CD4+ TRM cells expressing IFNγ or IL-17A were similar between mice with or without colitis." (PMID 35844584, 2022). "In another murine study on a model of anti-CD40 colitis, THC was also able to reduce the circulating levels of TNF-α, interleukin 17A (IL-17A), interleukin 22 (IL-22), and interferon-γ (IFN-γ), leading to a significant reduction in both systemic and local inflammation." (PMID 36289755, 2022).
colitis (continued). "Interestingly, in the murine colitis model, we demonstrate that an increased frequency of STAT3 GOF Tregs that had downregulated Foxp3 expression became IL-17A–producing ex-Tregs." (PMID 36136607, 2022). "Although colitis in this model was accredited to the production of the Th1 cytokine IFN-γ, enhanced emergence of IL-17A+IFN-γ population of T cells and suppression of populations of Foxp3+ and IL-10-producing regulatory T cells was attributed to IL-23R signalling in T cells." (PMID 36012618, 2022). "Moreover, dysregulated microbiota-triggered TGF-β1 influenced FGF-2 production in Treg cells during colitis, and cooperative effects between FGF-2 and IL-17A contributed to the regeneration of damaged intestinal epithelium." (PMID 36064450, 2022). "Percentages of IL-17A– or IFNγ-expressing CD4+ T cells were increased, whereas percentages of IL-17A– or IFNγ-expressing CD8+ T cells were not changed in mice with colitis compared with control mice." (PMID 35844584, 2022). "Transfer of Tbx21–/– naïve CD4+ T cells into Rag2–/– mice gives rise to a higher proportion of IL‐17A‐producing CD4+ T cells and more severe colitis compared to mice receiving WT naïve CD4+ T cells, suggesting that T‐bet restrains pathology in IL‐17‐driven colitis." (PMID 35092032, 2022). "In this study, CD4+CCR7+/− cells in mice with DSS-induced colitis were overactivated, and their subsets CD4+CCR7+IL-17A+ and CD4+CCR7−IL-17A+ increased significantly, while CD4+CCR7+IL-10+, CD4+CCR7−IL-10+, CD4+CCR7+Foxp3+, and CD4+CCR7−Foxp3+ decreased significantly." (PMID 35832382, 2022). "Recently, the suppression of IL-17F, but not of IL-17A, was found to protect against colitis by inducing Treg cells." (PMID 34395637, 2021). "Antibody against IL-17F was effective in treating chemically induced colitis, while antibody to IL-17A was not." (PMID 34539646, 2021). "The mice develop (histological) inflammation at the axial and peripheral entheses 1 week after curdlan induction followed by development of clinical enthesitis, sacroiliitis, peripheral arthritis and colitis and uveitis with increased serum levels of IFN-γ, TNF-α, IL-6 and IL-17A." (PMID 34267743, 2021). "Interestingly, after treatment with L.p R3 or/and MSLZ, the peripheral blood IFN-γ, IL-17A, and IL-17F levels were significantly decreased (p < 0.05), but blood IL-10 levels were significantly increased (p < 0.05) in the DSS-induced colitis mice." (PMID 34407839, 2021). "Comparing cytokine concentrations, significantly higher level of pro-inflammatory cytokines IL-6 and IL-17A and anti-inflammatory cytokine IL-10 were found in DSS-induced colitis group (p < 0.05, p < 0.001 and p < 0.001, respectively) compared to all other groups." (PMID 33540919, 2021). "Therefore, L.p R3 strain inhibits the expression of IFN-γ and IL-17A, while promotes the expression of CD25, Foxp3 and IL-10 in murine DSS-induced colitis tissue." (PMID 34407839, 2021). "Compared to untreated controls, treatment with antimiR-31 in both colitis models improved intestinal histology and weight recovery, and showed a marked decrease in IFN-γ+Th1 and IL-17A+ Th17 cell populations, indicating a role in alleviating inflammation via the regulation of Th1/Th17 response." (PMID 34571853, 2021). "Evidences have demonstrated that H. pylori infection decreased the pro-inflammatory cytokines (TNF-α, IFN-γ, IL-1β, IL- 6, IL-17A and IL23) in colitis mouse models, and we also have reported that IL-6 and IL23 expression were down-regulated in H. pylori-infected chronic colitis mice." (PMID 33201893, 2020). "Collectively, attenuated colitis requires increased IL-17A in the colorectum, but not IL-17F, to initiate protective factor synthesis." (PMID 32391010, 2020). "Acute intestinal inflammation due to DSS and TNBS was attenuated in IL-17A knockout mice, whereas chronic colitis was not relieved by T cell transfer from Il17a−/− mice (% of original body weight: wild-type mice vs. Il17a−/− mice, 81.9% vs. 82.2%; P = 0.922)." (PMID 31941937, 2020).
colitis (continued). "More importantly, predominant Th1 and Th17 responses present as colitis-related abundant CD4+ IFN-γ+ Th1 and CD4+ IL17+ Th17 cells that infiltrate into the colon mucosa LP, and colitis-mediated upregulated IFN-γ and IL-17A mRNA transcripts in the intestinal tissues were found in colitis mice." (PMID 32855978, 2020). "Our results showed that the expression of IL-17A target genes OCLN and IL-22 decreased in the colorectum of ArgmyeKO mice during colitis, which likely contributed to disruption of the intestinal barrier integrity thereby aggravating colitis." (PMID 32391010, 2020). "Both in the DSS-induced colitis model and in the colitis model induced by adoptive transfer of naive T cells, BDNs prevented intestinal damage and determined a reduction in the expression of TNF-α, IL-17A, and IFN-γ and an increased expression of IL-10." (PMID 33336066, 2020). "IL-17A expressed by TH17 cell increased obviously in PP and mLN, whereas IL-17F levels decreased in the presence of high levels of MDSC-derived Arg-1, proving once again that TH17 cell polarization is facilitated by Arg-1 expressed by MDSC during colitis." (PMID 32391010, 2020). "We aimed to evaluate the role of RORγt+ innate lymphoid cells (ILCs) in murine colitis models in the absence of IL-17A." (PMID 31941937, 2020). "Soybean-derived dipeptides and tripeptides decreased the colonic expressions of proinflammatory IFNG, IL-1B, IL-12B, TNF, and IL-17A and MPO activity and increased Foxp3 expression and CD4+CD25+ T cells; therefore, the colon and ileum inflammation of piglets with DSS-induced colitis was attenuated." (PMID 32963495, 2020). "Inhibition of IFN-γ, IL-17A or IL-17F during the chronic phase of colitis had no clear effect on chronic colonic or systemic inflammation." (PMID 31296924, 2019). "IL-17F-deficiency improves the development of DSS-induced murine colitis, whereas IL-17-deficiency exaggerates the development of DSS-induced murine colitis, indicating that IL-17F rather than IL-17A is important in sustaining DSS colitis." (PMID 31886308, 2019). "Furthermore, cLP ILCs from T-betΔNCR+ILC DSS-colitis mice produced higher IL-13 and IL-5 after stimulation than ILCs from DSS-WT mice, whereas IL-17A and IFNγ production by ILCs were equivalent in both groups." (PMID 30356098, 2019). "Consistently, several experimental colitis models revealed that absence or inhibition of IL-23 but not so much IL-17A or IL-17RA reduced gut inflammation." (PMID 30038617, 2018). "In contrast, when IL17A and IL17F were neutralized in the presence of IFNγ-producing cells, the histopathological assessment revealed severe colitis although the total score was slightly lower in anti-IL17A and IL17F treated mice compared to untreated recipient mice (data not shown)." (PMID 29416538, 2018). "The findings of a disease-attenuating effect of IL17A in some, but not all, mouse models of colitis is also reflected in human studies that showed exacerbation of intestinal inflammation in IBD patients treated with IL17 targeting biologicals." (PMID 29416538, 2018). "Colitis induction in the absence of IFNγ-producing T cells is preferentially driven by Th17-related mediators including IL17A and IL17F." (PMID 29416538, 2018). "IL-17A knockout (KO) mice were protected against 2,4,6-Trinitrobenzenesulfonic acid solution (TNBS)-induced colitis, and similarly, IL-17F KO mice had less severe DSS-colitis; however, interestingly, IL-17A KO mice had worse DSS-induced inflammation." (PMID 30103486, 2018). "Nevertheless, the present study showed similar results to a previous study which used a similar colitis model, where IL-17A levels were not influenced by the presence of TNFα and IL-1β." (PMID 30127744, 2018). "IL-17F, at difference to IL-17A, is not required in several T-cell-dependent autoimmune diseases in mice, while being pathogenic in DSS colitis model and in acute allergic responses in the lung." (PMID 30127781, 2018).
colitis (continued). "This leads to abnormally low frequencies of iTregs, breakdown of intestinal tolerance manifested by high frequencies of inflammatory IL-17A- and IFN-γ-producing T cells and high titres of commensal-specific IgA accompanied by commensal dysbiosis as results of severe colitis." (PMID 28276457, 2017). "Interestingly and in contrast with the data obtained using IL-17A knock-out mice, IL-17F knock-out mice show a less severe DSS-induced colitis." (PMID 29118756, 2017). "In particular, treatment with two specific MALT1 inhibitors, MI-2 and mepazine, dose-dependently attenuated the symptoms of colitis in mice through a decrease in protein and mRNA levels of colonic TNF, IL-1β, IL-6, IL-18, IL-17A, and IFN-γ pro-inflammatory cytokines." (PMID 28179906, 2017). "In the presence of T-bet, IL-23-driven colitis is multifunctional in nature and not functionally dependent on either IL-17A or IL-22." (PMID 27193261, 2016). "It has been widely accepted that Th1 response dominates in the TNBS-induced colitis while IL-17A seems not to be necessary in the T-cell mediated model of colitis." (PMID 26728323, 2016). "Because TNBS-induced colitis leads to marked inflammation in a pattern that is similar to that described for CD, the levels of the proinflammatory cytokines IL-12, IFN-γ, TNF-α, IL-6 and IL-17A were analysed." (PMID 27576902, 2016). "Mice lacking MHCII selectively on ILCs3 exhibit increased frequencies of proliferating CD4+ T cells in the blood, significant increase in commensal bacteria-specific serum IgG, and development of colitis characterized by enhanced production of IFN-γ, IL-17A, and TNF by mucosal CD4+ T cells." (PMID 25061260, 2014). "In these mutants, ILCs3 produce high levels of IL-17A, a finding not observed in control mice, and depletion of all ILCs or neutralization of IL-17A improves colitis." (PMID 25061260, 2014). "Furthermore, it has been recently reported that a novel subset of helper CD4+ T cells producing IL-17A, namely Th17 cells, is also involved in progression of DSS-induced colitis." (PMID 24686517, 2014). "Taken together, our results may highlight a novel aspect of IECs as a IL-17A-inducer in murine colitis, and that costimulatory molecules in IECs such as CD80/CD86 and CD40 may be a therapeutic target for colitis." (PMID 24255712, 2013). "This may partly be because mTORC1 inhibition decreases the expression of IL-23R on CD4+ T cells, a receptor for cytokine (IL-23) that is required for the induction of IL-17A/IFN-γ double-positive T cells and exacerbates the clinical course in murine colitis." (PMID 23383714, 2013). "A recent study suggested that IL-17F, but not IL-17A, was required to induce severe immunopathology in the dextran sulfate sodium-induced colitis model." (PMID 23956763, 2013). "ILCs were the primary source of IL-17A in this disease, and ILC depletion reversed colitis." (PMID 23063332, 2012). "Furthermore, IL-17A prevented and IL-17F exacerbated IFN-γ production and tissue destruction in a dextran sodium sulfate colitis model." (PMID 22577359, 2012). "In contrast to effects on isotype-control-treated mice, anti-CD90 substantially reduced the number of CD90+ cells and the number of IL-17A-producing cells in TRUC mice and ameliorated disease, including significantly improving colitis scores, reduced colon mass, and reduced spleen mass." (PMID 23063332, 2012). "Crucially, Tbx21−/−Rag2−/−Il2rg−/− mice had severely diminished numbers of intestinal ILCs, failed to develop colitis, and had undetectable levels of Il17a messenger RNA (mRNA) in the colon." (PMID 23063332, 2012). "As well as ameliorating H. typhlonius-induced colitis in TRnUC mice, TNF-α blockade also substantially reduced colonic Il17a transcripts, consistent with the possibility that TNF-α-augmented IL-17A production is physiologically relevant in ILC-mediated colitis." (PMID 23063332, 2012).